SIRT1 (sirtuin 1)
Diseases named in the same sentence as SIRT1 in open-access papers (continued):
Sharing a sentence is not in itself a finding about the gene and the disease.
rheumatoid arthritis (continued). "This study sought to assess the role of SIRT1 in rheumatoid arthritis (RA) using a myeloid cell-specific SIRT1 knockout (mSIRT1 KO) mouse." (PMID 24498364, 2014). "Antioxidant stress presents new mechanisms in mediating RA ferroptosis, where SIRT1 is transcriptionally suppressed by YY1 and inhibits ferroptosis in rheumatoid arthritis." (PMID 38965216, 2024). "In addition, DCs derived from patients affected by rheumatoid arthritis (RA) possess an increased expression of SIRT1 which determines the increased inflammatory response of this autoimmune pathology." (PMID 35457169, 2022). "Upregulation of SIRT1 by resveratrol suppressed the BK-induced COX-2/PGE2 production through inhibiting the interaction of AP-1 and NF-κB with COX-2 promoter in rheumatoid arthritis synovial fibroblasts." (PMID 35990040, 2022). "Higher expression of SIRT1 and FOXO3 has been reported in diabetic patients and in rheumatoid arthritis synovial fibroblasts." (PMID 35153741, 2021). "Recent studies suggest that SIRT1 may also impact inflammatory response and the proliferation of FLSs in rheumatoid arthritis (RA)." (PMID 29179491, 2017). "Notably, the expression level of IL-38 is abnormal in rheumatoid arthritis (RA) patients, and IL-38 can restrain inflammatory responses in collagen-induced arthritis (CIA) mice via Sirtuin1/Hypoxia-inducible factor-1α (SIRT1/HIF-1α) signaling pathway." (PMID 34539413, 2021). "Levels of anti-SIRT1 autoantibodies were significantly higher in AS (P < 0.001) and psoriatic arthritis (PsA) (P < 0.01) patients but not rheumatoid arthritis (RA) patients compared with healthy controls." (PMID 30558548, 2018).
cervical carcinoma (42 papers, 2009 to 2026). A carcinoma arising from either the exocervical squamous epithelium or the endocervical glandular epithelium. "Moreover, SIRT1 expression in HPV-infected cervical cancers was associated with a poor clinical outcome." (PMID 32164347, 2020). "Together, these findings demonstrate that SOX4 enhances cisplatin resistance in cervical cancer through SIRT1-upregulated suppression of glycolysis." (PMID 41832199, 2026). "While direct therapeutic interventions targeting SIRT1 in cervical cancer are still under investigation, its role in key cellular processes makes it a potential candidate for future therapies." (PMID 41300302, 2025). "Research on SIRT1 in cervical cancer is less extensive, but emerging studies suggest its involvement in tumor progression and response to therapy." (PMID 41300302, 2025). "In summary, SIRT1 plays an important role in the pathogenesis and progression of cervical cancer through its effects on cell proliferation, metastasis, chemoresistance, immune evasion, and viral replication." (PMID 41300302, 2025). "In cervical cancer, SIRT1 plays a complex role that can either promote tumor progression or tumor suppression, depending on the cellular context." (PMID 41300302, 2025). "SIRT1 contributes to chemoresistance in cervical cancer by modulating key signaling pathways such as β2-adrenergic receptor (β2-AR) signaling." (PMID 41300302, 2025). "High SIRT1 expression predicts a poor response to neoadjuvant chemotherapy (NAC) in locally advanced cervical cancer." (PMID 41300302, 2025). "SIRT1 is significantly overexpressed in cervical cancer tissues compared to normal cervical epithelium." (PMID 41300302, 2025). "Nevertheless, further research is warranted to fully elucidate SIRT1’s mechanisms and to develop targeted therapies for improved clinical outcomes in cervical cancer patients." (PMID 41300302, 2025). "SIRT1 has garnered significant attention in the context of gynecologic cancers—especially in ovarian, endometrial, and cervical cancers—due to its multifaceted roles in tumor progression, chemoresistance, and cellular metabolism." (PMID 41300302, 2025). "While SIRT1 is often considered to play a pro-tumorigenic role in cervical cancer, it can also function as a tumor suppressor under certain conditions." (PMID 41300302, 2025). "SIRT1 is also overexpressed in paclitaxel-resistant cervical cancer cells, and the knockdown of SIRT1 inhibits cell proliferation and promotes apoptosis, suggesting its role in mediating resistance." (PMID 41300302, 2025). "In cervical cancer, H19 acts as a miR-138-5p sponge, reducing SIRT1 expression as a miR-138-5p target gene." (PMID 38166752, 2024). "With nearly all cases of cervical cancer having been caused by high-risk HPV, understanding the interaction between HPV infection and tumorigenesis has illuminated the role of SIRT1 in aiding and protecting HPV-infected cells and promoting tumorigenesis." (PMID 39272943, 2024). "In cervical cancers, SIRT1 begins to be overexpressed in squamous intraepithelial neoplasia and squamous cell carcinoma and continues to increase as the disease progresses." (PMID 39272943, 2024). "In HPV‐infected cervical cancer cells, sirtuin 1 (SIRT1) is overexpressed and represses NF‐κB‐driven transcription of the AIM2 gene along with pyroptotic death signaling." (PMID 37752941, 2023). "In cervical cancer cells, SIRT1 can suppress pyroptosis by interfering with the transcription of AIM2." (PMID 35281845, 2022). "SIRT1 depletion inhibited proliferation, migration, and invasion and induced apoptosis of SiHa cervical cancer cells." (PMID 36558430, 2022). "Recent studies have reported that ADRB2 activation upregulates SIRT1 expression in cervical cancer cells through promoting the expression of c-MYC31." (PMID 34836959, 2021).
cervical carcinoma (continued). "LncRNA H19 sponges miR-138-5p, which directly targets SIRT1, and then affects progression of cervical cancer cells." (PMID 33390953, 2020). "SIRT1 may contribute to cervical cancer development by modulating pathways related to cell proliferation and apoptosis." (PMID 41300302, 2025). "SIRT1, a nicotinamide adenine dinucleotide-dependent deacetylase, may be a potential target for cervical cancer therapy." (PMID 38216595, 2024). "However, in contrast, H19 has been shown to upregulate SIRT1 and promote cervical cancer progression via sponging of miR-138-5p." (PMID 38166752, 2024). "In cervical cancer, it was reported that miR-29a-3p also targets SIRT1." (PMID 35163570, 2022). "However, AIM2 expression is inhibited by the deacetylase Sirtuin 1 (SIRT1) through the destabilization of RELB messenger RNA in HPV‐infected cervical cancer, assisting HPV‐infected tumors in escaping antiviral immunity." (PMID 34014039, 2021). "Furthermore, SIRT-1 is upregulated in HPV-infected cervical cancer, which facilitates continuous growth." (PMID 34522213, 2021). "Another report showed that HuR regulates SIRT1 expression in human cervical carcinoma HeLa cells." (PMID 33273545, 2020). "Regarding gynecologic cancer entities, the role of SIRT1 is studied in cervical cancer." (PMID 32388637, 2020). "Fittingly, SIRT1 expression correlates with poor survival in cervical cancer patients." (PMID 31861809, 2019). "Finally, an interesting interplay between AIM2 and the NAD+-dependent protein deacetylase Sirtuin 1 (SIRT1) has recently emerged in HPV-induced cervical cancer." (PMID 31861809, 2019). "Inhibitors of SIRT1, such as EX527, or thiocyanates, have demonstrated efficacy in impairing cervical cancer cell growth and inducing cell death." (PMID 41300302, 2025). "In this study, we explored the role of NAD+ metabolism in the regulation of PD‐L1 expression and nuclear localization in cervical cancer, with a spotlight on the NAMPT/SIRT1 axis." (PMID 39988985, 2025). "In the study of oridonin inhibiting the proliferation of human cervical cancer HELA cells and myeloma RPMI8266 cells, it was found that autophagy was activated and the expression level of SIRT1 increased." (PMID 35242756, 2022). "Previous studies have shown that miR-29a was low expression in cervical cancer, as a tumor suppressor, miR-29a can target multiple genes, such as CDC42, HSP47, SIRT1 and DNMT1." (PMID 33150075, 2020). "However, WRN and SIRT1 mRNA levels have an inverse relationship in CIN and cervical cancer; WRN levels reduce with increasing CIN grades while SIRT1 increases." (PMID 36230545, 2022). "A study using sirtuin 1 (SIRT1) knockdown showed that SIRT1 has been shown to induce metabolic reprogramming by increasing mitochondrial respiration and repress the NF‐κB‐driven transcription of AIM2, contributing to cervical cancer pathology in patients." (PMID 33682108, 2021). "BBR was shown to increase SIRT1 expression and activate AMPK in human cervical carcinoma cells." (PMID 33390968, 2020). "Similarly, SIRT1 overexpression induced by HPV impairs AIM2-mediated immunity, and this inhibition allows HPV-infected cervical cancer cells to escape death and continue their growth." (PMID 32164347, 2020).
cervical carcinoma (continued). "Although these studies suggest that SIRT1 may serve as a biomarker for predicting cervical cancer progression, it is not clear if the increased SIRT1 levels are part of a compensatory mechanism attempting to counteract cancer progression." (PMID 36558430, 2022). "Moreover, knockdown of SIRT1 not only result in pyroptosis of HPV-infected cervical cancer cells, such as SiHa cells, but it also induces pyroptotic cell death of naïve cervical cancer cells by releasing extracellular vesicles carrying AIM2 inflammasome proteins." (PMID 31861809, 2019). "Furthermore, SIRT1 allows HPV-infected cervical cancer cells to maintain growth levels by nullifying absent in melanoma 2 (AIM2) inflammasome-mediated immunity, and silencing SIRT1 causes these cancer cells to undergo pyroptosis regulated by EVs carrying AIM2 inflammasome proteins." (PMID 38216595, 2024). "However, the role of SIRT-1 in cervical cancer is not clear." (PMID 36558430, 2022).
autoimmune disease (41 papers, 2011 to 2025). A disorder resulting from loss of function or tissue destruction of an organ or multiple organs, arising from humoral or cellular immune responses of the individual to their own tissue constituents. "Anti-aging gene Sirtuin 1 (SIRT1) is associated with autoimmune diseases and irreversible programmed cell death in various cells and tissues." (PMID 37720208, 2023). "Accordingly, SIRT1-KO mice exhibit a more pro-inflammatory T cell phenotype and increased T cell proliferation and are more susceptible to develop autoimmune diseases." (PMID 34828304, 2021). "SIRT1 has been linked to immune-related diseases such as tumors and autoimmune diseases and was decreased in the PBMCs of multiple sclerosis patients during relapses." (PMID 34603387, 2021). "Importantly, SIRT1 plays a role in the disease susceptibility of T2D and its associated complications, and some studies have suggested that SIRT1 gene variants influence autoimmune diseases." (PMID 37695462, 2024). "Besides macrophages, SIRT1 has been shown to inhibit T cell activation, and its deficiency results in the breakdown of T cell tolerance, thus promoting autoimmune diseases." (PMID 34828304, 2021). "Deletion of SIRT1 in AgRP neurons induces a pro-inflammatory state, which is associated with a decrease in regulatory T cell functions and consequent increase in effector T cell activity, leading to increased autoimmune disease susceptibility in mice." (PMID 30416425, 2018). "In view of this, a mutation in the SIRT1 gene could lead to autoimmune disease." (PMID 33330467, 2020). "The regulatory mechanisms involving transcriptional and metabolic pathways identified in our work have been supported by prior research, providing further insights into the potential of targeting SIRT1 for immune modulation in cancer and autoimmune diseases." (PMID 39845948, 2024). "The subgroup analysis focusing on immune system diseases demonstrated a significant positive correlation between inflammation and SIRT1 levels in individuals with autoimmune diseases." (PMID 39676853, 2024). "Research has shown that by activating SIRT (e.g., SIRT1), we can limit the development of autoimmune diseases such as RA." (PMID 36675041, 2023). "Ablation of SIRT1 leads to increased activation of T cells and the onset of spontaneous autoimmune diseases." (PMID 35056739, 2022). "According to previous reports, only SIRT1, SIRT6, and rarely SIRT7 in the sirtuin family have been associated with dermatologic issues, such as skin aging, skin inflammation, autoimmune disease, cutaneous infection/cancer, and inherited dermatologic disease." (PMID 34122721, 2021). "IL-38, a novel cytokine of IL-1F, is expressed in SLE, RA, psoriasis, IBD, and other autoimmune diseases with different expression levels of IL-38 via different signaling pathways, such as SIRT1/HIF-1α signaling pathways." (PMID 34539413, 2021). "If specific regulatory role between IL-38 and SIRT1/HIF-1α signaling pathway in autoimmune diseases is clearly understood, it will provide new methods for treatments." (PMID 34539413, 2021). "Summary of immune regulatory pathways and their interaction with SIRT1 in modulating autoimmune diseases (ADs)." (PMID 33330467, 2020). "SIRT1, a class III histone/protein deacetylase (HDAC), has been associated with autoimmune diseases." (PMID 32485674, 2020). "In the following sections of this review, we will elaborately discuss T cell mediated SIRT1 roles in multiple ADs (section “The Role of SIRT1 in Autoimmune Disease”)." (PMID 33330467, 2020). "The pro-inflammatory role of SIRT1, at least partially caused by an inhibitory effect on FOXP3 stability and function, makes SIRT1 a potentially interesting target for the treatment of autoimmune disease." (PMID 30792714, 2019). "Collectively, these data demonstrate that, although opposite effects, both SIRT1 and 3 can be regarded as a potential therapeutic target in autoimmune disease." (PMID 30792714, 2019).
autoimmune disease (continued). "The ablation of Sirt1 leads to the enhancement of T cell activation and the occurrence of spontaneous autoimmune disease." (PMID 31035454, 2019). "Due to its aptitude to activate Sirt1 and suppress inflammation, resveratrol is able to alleviate inflammatory symptoms in several experimental autoimmune disease models, such as colitis, type I diabetes, encephalomyelitis, and rheumatoid arthritis." (PMID 31035454, 2019). "Pharmacological modulation of SIRT1 activity has been used as a therapeutic strategy in autoimmune disease settings." (PMID 30622543, 2018). "This compound is also key in the inhibition of inflammatory transcription factors, such as NF-κB and SIRT1—major regulators of the inflammatory response in some autoimmune diseases." (PMID 29194364, 2017). "Our previous study demonstrated that Sirt1 maintains periphery T cell tolerance, and that the ablation of Sirt1 leads to the enhancement of T cell activation and spontaneous autoimmune disease." (PMID 24073240, 2013). "Our findings support that Sirt1 is required for anti-inflammation of resveratrol and suggest that Sirt1 is an important target for treatment of autoimmune disorders." (PMID 22069489, 2011). "The results of studies on SIRT1 levels in autoimmune diseases have been found to vary greatly." (PMID 40757915, 2025). "The results of the immune system disease subgroup analysis, revealed that in the autoimmune disease group, the SIRT1 concentration in the case group was 1.46 ng/mL higher than in the control group (WMD, 1.46 ng/mL; 95% CI 0.16, 2.77 ng/mL; P= 0.027; I2 = 99.5%)." (PMID 39676853, 2024). "SIRT1 controls inflammation, oxidative stress, immune responses, cell differentiation, and proliferation, as well as cell metabolism, and is therefore likely involved in autoimmune diseases (ADs)." (PMID 36675041, 2023). "SIRT1-deficient mice have immune complexes deposited in their livers and kidneys, suggesting an autoimmune disease due to the absence of SIRT1." (PMID 35406621, 2022). "However, data on the assessment of sirtuin 1 and IL-27 in relation to CV parameters in autoimmune diseases are limited." (PMID 34439776, 2021). "Thus far, most studies have indicated that decreased SIRT1 expression or activity contributes to the enhancement of lymphocyte activation, thereby leading to the occurrence of autoimmune disease." (PMID 33981300, 2021). "Sirtuin 1, the epigenetic enzyme that regulates various cellular pathways, has attracted significant attention over recent years because it is involved in the pathogenesis of both CV diseases and autoimmune disorders." (PMID 34439776, 2021). "The up-regulation or down-regulation expression level of IL-38 may affect different types of autoimmune diseases via different signaling pathways, for instance, SIRT1/HIF-1α signaling pathway." (PMID 34539413, 2021). "FOXP3, RORγt, STAT3, RelA/p65 (NF-κB), and c-Fos/c-Jun (AP-1) are transcription factors targeted by SIRT1, which are well-studied and are crucial to a balanced immune system, but the role of SIRT1 in autoimmune disease is only in the incipient stage, especially in the progression of SLE." (PMID 33981300, 2021). "In line with what was demonstrated in Sirt1 knock-out mice, selective inhibition of SIRT1 with small-molecule inhibitors promoted Treg cell numbers and function in in vitro studies using primary human cells and in in vivo animal models for autoimmune diseases." (PMID 30792714, 2019). "On the other hand, SIRT1 generally inhibits Teff inflammation, suggesting that activators of SIRT1 could be useful for the treatment of autoimmune disease; however, the effects of SIRT1 on T cells vary by subset and are context-dependent." (PMID 31354630, 2019). "Sirt1 is involved in periphery T cell tolerance, ablation of Sirt1 in T cells could induce hyper-activation of T cells and lead to spontaneous autoimmune disease." (PMID 31035454, 2019).